RNU6-512P (RNA, U6 small nuclear 512, pseudogene)
Gene: Small nuclear RNA gene on chromosome 2 (135,656,477 to 135,656,579, reverse strand). Ensembl gene ENSG00000201308.
Homologues: Orthologues: chimpanzee U6 (100% identical), mouse Gm23185 (70% identical), guinea pig U6 (62% identical). Paralogues in human: RNU6-1 (77% identical), RNU6-11P (77% identical), RNU6-1329P (77% identical), RNU6-15P (77% identical), RNU6-2 (77% identical), RNU6-33P (77% identical), RNU6-36P (77% identical), RNU6-37P (77% identical), RNU6-38P (77% identical), RNU6-3P (77% identical), RNU6-4P (77% identical), RNU6-5P (77% identical), and 1282 more.